BCL2L12 (BCL2 like 12)
Tractability: Antibody: the Human Protein Atlas places it where antibodies can reach. PROTAC: ubiquitination databases record sites on it.
Gene: Protein-coding gene on chromosome 19 (49,664,622 to 49,673,916, forward strand). Ensembl gene ENSG00000126453.
Subcellular location (Human Protein Atlas): Vesicles; Plasma membrane
Gene Ontology:
Molecular function: protein binding
Biological process: negative regulation of apoptotic process; positive regulation of transcription by RNA polymerase II; regulation of apoptotic process
Cellular component: membrane; nucleus
Genetic constraint (gnomAD): Loss-of-function variants: 27 observed, 23.66 expected, observed/expected ratio (o/e) 1.14, 90% interval 0.84 to 1.57. The upper end of that interval is the gene's LOEUF score, 1.57, which puts it in group 6 of 6, group 1 being the genes least tolerant of losing a copy. Missense variants: 302 observed, 291.12 expected, observed/expected ratio (o/e) 1.04, 90% interval 0.94 to 1.14. Synonymous variants: 132 observed, 133.31 expected, observed/expected ratio (o/e) 0.99, 90% interval 0.86 to 1.14.
Homologues: Orthologues: chimpanzee BCL2L12 (99% identical), macaque BCL2L12 (96% identical), dog BCL2L12 (90% identical), guinea pig BCL2L12 (85% identical), rat Bcl2l12 (85% identical), mouse Bcl2l12 (84% identical), rabbit BCL2L12 (83% identical), tropical clawed frog bcl2l12 (35% identical), zebrafish bcl2l12 (34% identical). Paralogues in human: BCL2L14 (20% identical).
Diseases named in the same sentence as BCL2L12 in open-access papers:
BCL2L12 is named in the same sentence as 49 diseases in open-access papers, as found by Europe PMC text mining. Sharing a sentence is not in itself a finding about the gene and the disease. The quoted sentences say what the papers report.
glioblastoma (19 papers, 2019 to 2026). The most malignant astrocytic tumor (WHO grade IV). "This approach utilized GNPs conjugated with RNA nucleotides designed to target the Bcl2L12 protein, a key regulator of apoptosis in glioblastoma cells." (PMID 40236567, 2025). "NU-0129 is a spherical nucleic acid (SNA) siRNA that targets the glioblastoma oncogene BCL2L12 and crosses the BBB using the RMT strategy." (PMID 37430086, 2023). "For example, in glioblastoma, the Bcl2Like12 (Bcl2L12) oncoprotein tends to be overexpressed, leading to apoptosis inhibition." (PMID 36045273, 2023). "Bcl2L12 is a potential prognostic factor, as glioblastoma patients with high-level overexpression of Bcl2L12 mRNA have shorter progression-free survival than patients with low or underexpression of Bcl2L12." (PMID 35406387, 2022). "BCL2L12 is upregulated in human glioblastomas and blocks the activation of caspase-3 and caspase-7 to confer resistance to apoptosis." (PMID 36271053, 2022). "NU-0129 is a spherical nucleic acid gold nanoparticle containing siRNAs targeting Bcl-2-like protein 12 (Bcl2L12) is now in early phase I clinical trials (NCT03020017) for patients with recurrent glioblastoma." (PMID 33790740, 2021). "Once within the tumor, the nucleic acid component enables the targeting of Bcl2L12 gene, an upregulated gene in most human glioblastomas that plays a role in resistance to apoptosis." (PMID 32718058, 2020). "Moreover, the SNA display polyvalent interactions and have been claimed to be able to cross the blood–brain barrier, enabling delivery of siRNA to glioblastoma lesions and knockdown of Bcl2L12, promoting apoptosis and tumor shrinkage." (PMID 36045273, 2023). "Tissue microarray and immunohistochemistry analysis of archived glioblastoma tissue validated Bcl2L12 protein expression in most human glioblastoma specimens and revealed low or undetectable levels in cells of glial origin in normal brain surrounding tumor tissue or in low-grade astrocytoma." (PMID 35406387, 2022). "Accumulation and pervasive dissemination into extravascular tumor parenchyma translated into robust intratumoral Bcl2L12 protein knockdown, increased intratumoral apoptosis, impaired tumorigenicity as measured by reduced tumor burden, and prolonged survival of glioblastoma PDX-bearing mice." (PMID 35406387, 2022). "Bcl2L12 expression is increased in glioblastoma through multiple mechanisms, including gene amplification (as seen as a non-focal gain of chromosome 19(q)), transcriptional upregulation in the absence of gene amplification, and induction of the Bcl2L12-targeting miR-182." (PMID 35406387, 2022). "It is noted that BCL2L12 expression is upregulated in most human glioblastomas." (PMID 31001122, 2019). "For example, in one earlier study, they fabricated the RNAi-based SNA targeting oncogenes (Bcl2L12) which is traditionally untargetable by small molecules or antibodies in glioblastoma multiforme (GBM) pathogenesis." (PMID 34466734, 2022). "Additionally, NU-0129, a spherical nucleic acid gold nanoparticle containing siRNAs targeting Bcl-2-like protein 12 (Bcl2L12), which is involved in tumor progression and resistance to apoptosis, is in early phase 1 clinical trials for patients with recurrent glioblastoma or gliosarcoma." (PMID 30654536, 2019). "The safety profile of AuNPs has been supported by clinical trial data of BCL2 like 12 (Bcl2L12) siRNA-AuNP for treating glioblastoma, where no significant toxicity was observed in patients." (PMID 39962586, 2025).
glioma (10 papers, 2012 to 2025). A benign or malignant brain and spinal cord tumor that arises from glial cells (astrocytes, oligodendrocytes, ependymal cells). "In addition, RNAi loss-of-function studies demonstrated that Bcl2L12 neutralization sensitized glioma cells toward apoptosis, and most importantly, reduced intracranial tumor formation with increased apoptotic, decreased proliferative indices, and enhanced tumor-free survival." (PMID 22431925, 2012). "The signaling transduction proposed in this study is consistent with the oncogenic roles of EYA1 and BCL2L12 in glioma development as previously reported." (PMID 39897043, 2025). "Given that c-Myc is a known EYA1 substrate in other biological contexts, and BCL2L12 is an essential oncoprotein in glioma development, we decided to focus our further investigations on BCL2L12." (PMID 39897043, 2025). "Using unbiased phosphoproteomics combined with a novel screening strategy, we identify BCL2L12 as an EYA1 threonine phosphatase substrate in glioma cells." (PMID 39897043, 2025). "Pearson correlation analysis showed a positive correlation between EYA1 and BCL2L12 proteins in glioma patient samples." (PMID 39897043, 2025). "Taken together, these results demonstrate that EYA1 colocalizes and physically interacts with BCL2L12 in glioma cells." (PMID 39897043, 2025). "Collectively, these findings indicate that BCL2L12 partially mediates the oncogenic effects of EYA1 on glioma cell proliferation." (PMID 39897043, 2025). "In this study, we employed an unbiased phosphoproteomic approach and identified the essential glioma oncoprotein BCL2L12 as a novel substrate of EYA1 in glioma cells." (PMID 39897043, 2025). "We also describe a signaling pathway where EYA1 regulates BCL2L12 turnover by dephosphorylating T33, which contributes to glioma development." (PMID 39897043, 2025). "BCL2L12 is an important oncoprotein that promotes cell proliferation and prevents apoptosis in glioma." (PMID 39897043, 2025). "To evaluate the clinical relevance of EYA1 and BCL2L12 in glioma, we investigated their expression using immunohistochemical (IHC) staining on a glioma tissue microarray (TMA)." (PMID 39897043, 2025). "Next, we investigated the biochemical interaction between EYA1 and BCL2L12 in mammalian cells and its potential impact on glioma development." (PMID 39897043, 2025). "Taken together, these results suggest that EYA1-mediated dephosphorylation of BCL2L12 at T33 plays a crucial role in glioma tumor formation." (PMID 39897043, 2025). "In summary, this study identifies BCL2L12 as a new substrate for EYA1 threonine phosphatase activity in glioma development." (PMID 39897043, 2025). "In vitro experiments demonstrated that miR-182-SNAs were efficiently internalized and significantly reduced the levels of Bcl2L12 and c-Met proteins in gliomas." (PMID 38951806, 2024). "BCL2L12 (Bcl2-like 12) universally overexpressed in human glioma specimens and contributed to important disease characteristics, including resistance to chemotherapy-induced apoptosis." (PMID 37077419, 2023). "Both siRNA and miRNA-based SNAs robustly penetrated patient-derived glioma initiating cells (GICs) through SR-A engagement and triggered robust Bcl2L12 target knockdown." (PMID 35406387, 2022).
glioma (continued). "BCL2L12 plays a crucial role in regulating glioma cell growth and survival." (PMID 39897043, 2025). "Furthermore, we validated the regulatory relationship between EYA1 and BCL2L12 in glioma by examining protein expression in patient samples." (PMID 39897043, 2025). "Additionally, glioma patients with higher BCL2L12 mRNA levels experienced poorer overall and progression-free survival." (PMID 39897043, 2025). "Moreover, we validate a positive correlation between EYA1 and BCL2L12 protein levels in glioma patient samples." (PMID 39897043, 2025). "Additionally, we show that BCL2L12 partially mediates the oncogenic function of EYA1 in glioma cells in a dephosphorylation-dependent manner." (PMID 39897043, 2025). "We first evaluated the effects of EYA1 on BCL2L12 expression in glioma cells." (PMID 39897043, 2025). "To investigate the effects of the phosphorylation status of T33 in BCL2L12 on glioma development, we stably overexpressed various versions of BCL2L12 in U251MG cells, including wild-type (WT), phospho-mimic (T33E), and phospho-dead (T33A) mutant, and xenografted them into the immunocompromised mice." (PMID 39897043, 2025). "We then asked whether BCL2L12 could mediate the oncogenic effects of EYA1 on glioma development." (PMID 39897043, 2025). "In this study, we identify BCL2L12 (BCL2-like 12), a critical oncoprotein in glioma, as a novel substrate of EYA1 phosphatase in glioma cells." (PMID 39897043, 2025). "Our results indicate that BCL2L12 partially mediates the oncogenic roles of EYA1 in promoting glioma cell proliferation, highlighting the significance of EYA1's dephosphorylation of BCL2L12 in tumor progression." (PMID 39897043, 2025). "In glioma patient samples, EYA1 was predominantly found in the nucleus, whereas BCL2L12 was mainly nuclear but also weakly detectable in the cytoplasm." (PMID 39897043, 2025). "In our study, enforced EYA1 expression increases BCL2L12 expression in glioma cells, and, conversely, silencing EYA1 results in downregulation of BCL2L12." (PMID 39897043, 2025). "Our study reveals that EYA1 controls the turnover of BCL2L12 by regulating BCL2L12 dephosphorylation and stabilization, implicating EYA1 as a potential therapeutic target for glioma treatment." (PMID 39897043, 2025). "We found that, besides the well-established c-Myc, only BCL2L12 met both criteria in our phosphoproteome data, suggesting that BCL2L12 might be a potential EYA1 substrate in glioma cells." (PMID 39897043, 2025). "To distinguish whether BCL2L12 is regulated by the proteasome or lysosome mediated degradation pathways, we conducted rescue experiments in EYA1 knockdown glioma cells using the proteasome inhibitor MG132 and the lysosome inhibitor chloroquine (CQ)." (PMID 39897043, 2025). "We demonstrate that BCL2L12 interacts and colocalizes with EYA1 in glioma cells." (PMID 39897043, 2025). "Moreover, the protein expression level of EYA1 and BCL2L12 is positively correlated in glioma patient samples, suggesting that this positive regulatory relevance between EYA1 and BCL2L12 is also important in clinical settings." (PMID 39897043, 2025).
melanoma (10 papers, 2014 to 2025). A malignant, usually aggressive tumor composed of atypical, neoplastic melanocytes. "To better characterize the cluster, we analyzed BCL2L12 mutation load in 1,076 melanoma samples in the catalog of somatic mutations in cancer (COSMIC)." (PMID 40359938, 2025). "A first example illustrating this concept is the chr19:49665874 C > T (GRCh38/hg38) mutation, which was described in 2013 as a synonymous p.Phe17Phe mutation targeting the BCL2L12 oncogene in 4% of melanoma skin cancers." (PMID 41278537, 2025). "Analysis of RNA-sequencing (RNA-seq) data from human melanoma samples revealed that this variant is an upstream noncoding BCL2L12 variant in respect to the BCL2L12 transcripts that are expressed." (PMID 41278537, 2025). "Recently, synonymous somatic mutations in BCL2L12 have been reported to increase BCL2L12 mRNA and protein levels during the development of melanoma." (PMID 32241263, 2020). "For instance, synonymous somatic mutant BCL2L12 was associated with higher anti-apoptotic activity than the wild type in melanoma." (PMID 30650643, 2019). "Yardena Samuels and colleagues identified somatic mutations in 29 melanoma samples and found an interesting synonymous mutation in the Bcl-2-like protein 12 (BCL2L12) gene that is as an anti-apoptotic factor (a C to T change at position 51 (F17F))." (PMID 28536625, 2016). "Interestingly, IRF3 and BCL2L12 mRNA expression was significantly reduced in melanoma tumors with an IRF3/BCL2L12 promoter mutation as compared to tumors with a wild-type promoter region." (PMID 40359938, 2025). "Additionally the functional synonymous mutation described in BCL2L12 (located at chr19:50169131) is present within the 34 melanoma exomes, 170 clinical melanoma samples and within the cSCC data set." (PMID 27611953, 2016). "Illumina-based RNA-seq as well as direct cDNA long-read nanopore sequencing confirmed that Mel-ST cells express the same IRF3 and BCL2L12 isoforms as we had observed in melanoma tumors." (PMID 40359938, 2025). "To assess the functionality of the identified IRF3/BCL2L12 promoter mutations, we evaluated their impact on IRF3 and BCL2L12 mRNA expression in melanoma tumor samples." (PMID 40359938, 2025). "By annotating to expressed transcripts, we identify a number of overlooked functional non-coding mutations in melanoma, including IRF3/BCL2L12 promoter mutations." (PMID 40359938, 2025). "As expected, this list included well documented frequent oncogenic drivers of melanoma, including hotspot mutations in BRAF, NRAS, RAC1, PPP6C, TRRAP, MAP3K5 and BCL2L12." (PMID 24913145, 2014). "Next, the three IRF3/BCL2L12 promoter mutations that we had identified in melanoma were each introduced heterozygously and without additional mutations into Mel-ST cells using CRISPR-Cas9." (PMID 40359938, 2025). "In addition, miR-671-5p has been showed to silence the SMARCB1 expression in epithelioid sarcoma and to repress BCL2L12 expression in melanoma." (PMID 26588055, 2016). "In melanoma, a synonymous c.51C>T (GenBank: NM_001282520.1) (p.Phe17=) mutation in the BCL2L12 (MIM: 610837) oncogene was shown to impair binding of miRNA hsa-miR-671-5p to the BCL2L12 mRNA, leading to BCL2L12 overexpression and cellular resistance to UV-induced apoptosis." (PMID 40359938, 2025). "Together with the first hotspot, these mutations have a combined frequency of 3.8%–5.5% and result in downregulation of BCL2L12 and IRF3 expression in melanoma tumors." (PMID 40359938, 2025).
melanoma (continued). "This, for instance, applies to the mutation clusters targeting known cancer genes kinetochore localized astrin (SPAG5) binding protein (KNSTRN) and BCL2-like 12 (BCL2L12), each affecting 4%–5% of melanoma tumors." (PMID 40359938, 2025). "Nevertheless, cancer genomics databases such as COSMIC and Genomics Data Commons are still annotating g.49665874C>T (GenBank: NC_000019.10) as synonymous, as they are using a BCL2L12 reference transcript that is not expressed in melanoma for annotation." (PMID 40359938, 2025).
colon cancer (7 papers, 2016 to 2023). "The mechanisms by which miR-125 regulate CRC forms a complex network, miR-125 could negatively modulate BCL2, BCL2L12, and Mcl-1, and down-regulated miR-125 promoted colon cancer cell proliferation and inhibited apoptosis." (PMID 31782506, 2019). "The prognosis of BCL2L12 negative colon cancer patients was significantly poorer than that of BCL2L12 positive colon cancer patients." (PMID 35395711, 2022). "Interestingly, miR-125a-5p was reported to be a direct regulator of the anti-apoptotic genes BCL2, BCL2L12, and Mcl-1 in colon cancer cells in a negative manner." (PMID 35846752, 2022).
breast carcinoma (5 papers, 2017 to 2023). "Additionally, BCL2L12 exerts pro-apoptotic effects implicated in various malignancies, including laryngeal squamous cell carcinoma, breast cancer, and acute myeloid leukemia." (PMID 34116684, 2021). "For example, novel PRMT1 circRNAs in breast cancer and BCL2L12 circRNAs in colorectal cancer share this feature, where several nucleotides at the exons forming the back-splice junction are identical." (PMID 37888203, 2023). "ERβ5 in breast cancer cells has been found to enhance apoptosis induced by chemotherapeutic agent through Bcl2L12 interaction." (PMID 28859612, 2017).